RNU7-71P (RNA, U7 small nuclear 71 pseudogene)
Synonyms: U7.71
Gene: Small nuclear RNA gene on chromosome 16 (72,821,933 to 72,821,992, reverse strand). Ensembl gene ENSG00000251868.
Homologues: Orthologues: chimpanzee U7 (97% identical), macaque U7 (93% identical), pig U7 (80% identical). Paralogues in human: RNU7-60P (90% identical), RNU7-12P (88% identical), RNU7-13P (88% identical), RNU7-52P (88% identical), RNU7-65P (88% identical), RNU7-11P (87% identical), RNU7-2P (87% identical), RNU7-1 (85% identical), RNU7-160P (85% identical), RNU7-56P (85% identical), RNU7-63P (85% identical), RNU7-6P (85% identical), and 143 more.